STAT3 (signal transducer and activator of transcription 3)
Diseases named in the same sentence as STAT3 in open-access papers (continued):
Sharing a sentence is not in itself a finding about the gene and the disease.
lung carcinoma (continued). "A variety of intracellular molecules are also DTP inducers in EGFR-mutated lung cancers, including Aurora kinase A, ERK, NF-kB, STAT3, and β-catenin." (PMID 37920509, 2023). "OGT directly modifies STAT3, which enhances phosphorylation of STAT3 to promote metastasis in lung cancer." (PMID 37838167, 2023). "There are reports that STAT3 phosphorylation at Y705 is responsible for activating STAT3 to promote cell proliferation, enhance cell survival and proliferation, promote immune escape, and contribute to lung cancer malignant transformation." (PMID 36977736, 2023). "Given the critical roles of p38, ERK, AKT and STAT3 pathways in lung cancer’s initiation and progression, we further examined the influence of KDF1 overexpression in these pathways." (PMID 38137415, 2023). "The results of Zhang et al27 suggested that the overexpression of miR-4443 promoted the resistance to epirubicin-based chemotherapy of non–small-cell lung cancer cells via the activation of the Janus kinase 2 (JAK2)/STAT3 pathway." (PMID 36690076, 2023). "The constitutive activation of STAT3 protein has been implicated in several types of malignant tumors such as esophageal squamous cell carcinoma (ESCC), colorectal cancer, lung cancer, and gastric cancer." (PMID 36225196, 2022). "Dioscin inhibits TAM/M2 polarization through JNK and STAT3 signalling pathways, thereby inducing anti‐tumour immunity and inhibiting lung cancer angiogenesis." (PMID 36372977, 2022). "Among the studied chemokines and cytokines, IL-6, which was reported to induce EGFR-TKI resistance in EGFR-mutant lung cancer through paracrine STAT3 activation, was highly expressed in EGFR wild-type A549 cells in our study." (PMID 36612121, 2022). "Blocking IL-6 expression can inhibit lung cancer promotion, cell proliferation, angiogenesis markers, and tumor cell-intrinsic STAT3 activation." (PMID 36437827, 2022). "Numerous studies have shown that STAT3 is involved in multiple metastasis steps and plays an important role in the metastasis of different tumors, including lung cancer." (PMID 35178453, 2022). "The activities of SP‐1 and STAT3 induced by NF‐κB, USF1, and IL‐6 were not significantly affected by K284 treatment, but lipopolysaccharide‐ and TNF‐α‐induced SP‐1, STAT3, and AP‐1 were significantly decreased by K284 treatment in A549 lung cancer cells." (PMID 34758182, 2022). "About half of lung cancer patients have high expression of STAT3, and constitutive activation of this protein contributes to resistance to conventional therapies." (PMID 36224313, 2022). "We further propose a novel Stat3 dependent targetable mechanism, which is instrumental in mediating the migration and invasion of lung cancer cells." (PMID 36140747, 2022). "Subsequently, we assessed the pharmacological effects of YHO-1701 in ALK-rearranged lung cancer cells via inhibition of STAT3 nuclear translocation." (PMID 35228642, 2022). "During tumourigenesis, tumourigenic signals such as Cxcl1 and Ccl2 induce Pdia4 overexpression and Stat3 phosphorylation and, subsequently, lead to an up‐modulation of Vegf proteins in lung cancer stromata." (PMID 35170261, 2022). "Lusianthridin suppresses lung cancer stem cells via the inhibition of Src-STAT3-c-Myc; thereby, regulating the stemness of the cells." (PMID 36364058, 2022). "In this review, we will summarize the recent advances in STAT3 targeting strategies, as well as the applications of nanoparticle-mediated targeted delivery of STAT3 inhibitors in the treatment of lung cancer." (PMID 36559280, 2022). "In this study, our results showed that rhein have obviously affect in treatment of proliferation and metastasis of chemosensitive and chemoresistant lung cancer cells, and play a role via the Stat3/Snail/MMP2/MMP9 pathway." (PMID 35178453, 2022). "Together, these data demonstrate that JAK1/STAT3 signaling is activated in IL20RB-expressing lung cancer cells by osteoclast-secreted IL-19." (PMID 36006737, 2022).
lung carcinoma (continued). "There is evidence that abnormally activated STAT3 has been found in a variety of cancers, including lung cancer, which leads to the inactivation of apoptotic pathways and the resistance of cancer cells to radiotherapy and chemotherapy." (PMID 36559280, 2022). "It has been suggested that OSF-2 (in)directly contributes to cisplatin resistance in lung cancer cells via activation of Stat3, Akt, and up-regulation of the anti-apoptotic protein survivin." (PMID 35565465, 2022). "It is worth noting that STAT3 has also been reported to have a potential role in tumor suppression in addition to promoting the development of lung cancer." (PMID 36559280, 2022). "MUC16 performs a meaningful function in metastasis and tumourigenesis in lung cancer by regulating TSPYL5 through JAK2/STAT3/GR." (PMID 36059804, 2022). "Consistently, here we observe that TGF-β1 activates JAK2/STAT3 signaling in lung cancer cells, and overexpression of SH2B3 inhibits this activation." (PMID 35589677, 2022). "Overall, our results indicate that the treatment-induced adaptive survival of ALK-rearranged lung cancer cells is predominantly dependent on STAT3 activity." (PMID 35228642, 2022). "Our study reports for the first time that SH2B3 regulates EMT and anoikis resistance by inhibiting JAK2/STAT3 signaling in lung cancer." (PMID 35589677, 2022). "We investigated the functional roles of STAT3 in the adaptive survival of ALK-rearranged lung cancer cells by evaluating apoptosis induction with STAT3 knockdown." (PMID 35228642, 2022). "Signal transducer and activator of transcription-3 (Stat3) is a potential target for many cancers, including lung cancer." (PMID 35178453, 2022). "Considering our findings, a clinical trial is warranted to assess the efficacy of the new combination therapy co-targeting ALK and STAT3 in ALK-rearranged lung cancer." (PMID 35228642, 2022). "A novel circRNA (circHIPK3) increases STAT3 expression by inhibiting miR-124-3p in STK11 mutant lung cancer cells." (PMID 36338714, 2022). "The inhibitory effect of STAT3 phosphorylation by shikonin has already been shown in various tumor types, such as pancreatic cancer, melanoma, or lung cancer." (PMID 35820864, 2022). "We also found that Pdia4 activated Stat3 and its downstream pathways (e.g., increased expression of Vegf family), leading to a promotion of lung cancer development in mice." (PMID 35170261, 2022). "Recent evidence showed that the activated JAK/STAT3 pathway was a momentous signal for TGF-β1-induced EMT in lung cancer." (PMID 35216134, 2022). "Among the five PRlncRNAs included in the signature, the lncRNA PICART1 is closely associated with the suppression of lung cancer cell proliferation by targeting the AKT1 and JAK2/STAT3 signaling pathways." (PMID 35739504, 2022). "In a urethane-induced lung cancer model, myeloid STAT3 deletion resulted in improved anti-tumor immunity, with M2 macrophages replaced by the M1 phenotype." (PMID 35406557, 2022). "Another natural triterpenoid extracted from Anemone Raddeana Regel, Raddeanin A, was able to inhibit the expression of pSTAT3 and STAT3, reduce the mitochondrial membrane potential, and promote apoptosis in A549 and H1299 lung cancer cells." (PMID 36559280, 2022). "Circ AKT3 inhibits the cisplatin sensitivity of lung cancer cells via the miR-516b-5p/STAT3 axis-mediated glycolysis balance." (PMID 36338714, 2022). "IL-24-expressing oncolytic vaccine virus, against lung cancer, destructed cancer cells through apoptosis and induced a decline in the level of STAT3." (PMID 35752792, 2022). "This molecule regulates multidrug resistance in lung cancer through the PI3K/BMX/STAT3 signaling pathway." (PMID 36106335, 2022). "High expression of certain cytokines (including IL-6, IL-8, and TNF-α) was linked to cancer cachexia, as exemplified by that IL-6 enclosed in lung cancer-derived extracellular vesicles would evoke muscle wasting by activating STAT3 pathway." (PMID 36581870, 2022).
lung carcinoma (continued). "Activation of CXCR4 and STAT3 results in the initiation of multiple signaling pathways, leading to metastasis and angiogenesis in lung cancer; thus, CXCR4 and STAT3 are potential targets for anti-angiogenic therapy." (PMID 35918758, 2022). "Exosome-mediated transfer of select miRNAs, including miR-210-3p, miR-193a-3p, and miR-5100, facilitates the invasion of lung cancer cells via the activation of STAT3 signaling-induced EMT." (PMID 36233088, 2022). "The study proposes PGG as a potential AMPK activator and STAT3 inhibitor that can be exploited further in developing adjuvant chemotherapeutics against lung cancer." (PMID 35928273, 2022). "Epidermal growth factor receptor (EGFR) signaling has been shown to positively regulate G9a expression through signal transducer and activator of transcription 3 (STAT3) in EGFR+ lung cancer." (PMID 35740522, 2022). "Therapeutic RNA molecules, including antisense oligonucleotides (ASOs), small interfering RNAs (siRNAs), short hairpin RNAs (shRNAs), microRNAs (miRNAs), and long intergenic non-coding RNA (lncRNAs), have been developed for STAT3-targeted lung cancer therapy." (PMID 36559280, 2022). "In lung cancer, activation of Akt1/IL‐6/STAT3 pathway also contributes to maintaining the stemness of tumour initiating cells." (PMID 34997691, 2022). "In this study, we explored the novel role of MRE11 in the IL6/STAT3/CCL2 signaling pathway in lung cancer." (PMID 36547079, 2022). "Crizotinib induced cytoprotective autophagy by inhibiting STAT3 expression in lung cancer cells, which led to the development of drug resistance." (PMID 35559037, 2022). "In lung cancer, transfer of exosomal miR-193a, miR-210-3p, miR-5100 from hypoxic bone marrow MSCs promoted cancer cells’ invasion via signal transducer and activator of transcription 3 (STAT3) driven EMT." (PMID 35592419, 2022). "The interleukin-6 (IL-6)/Janus kinase (JAK)/signal transducer and activator of transcription 3 (STAT3) signaling pathway is overactive in multiple cancer types, including lung cancer, and is important in cancer pathogenesis." (PMID 34773474, 2022). "AZD9150, an antisense oligonucleotide containing a restricted ethyl modification targeting STAT3, reduced STAT3 expression in a wide range of preclinical cancer models and showed antitumor activity in lymphoma, neuroblastoma, and lung cancer models." (PMID 36291659, 2022). "Studies have found that IFN-γ can induce the expression of PD-L1 in A549 lung cancer cells through activating the Janus kinase/signal transducer and activator of transcription 3 (JAK/STAT3) signaling and the phosphatidylinositol 3-kinase (PI3K)/AKT signaling." (PMID 36186906, 2022). "Aberrant activation of Janus kinase 2 (JAK2)/signal transducer and activator of transcription 3 (STAT3) signaling has been reported in the progression of numerous cancers including lung cancer." (PMID 35589677, 2022). "Overall, in lung cancer cells, the Stat3 signaling pathway is the target, whereby rhein suppresses migration." (PMID 35178453, 2022). "NF-κB and STAT3 are critical regulators of tumor angiogenesis and invasiveness in pre-neoplastic and malignant lung cancer cells." (PMID 35745729, 2022). "TGF-β and IL-6/JAK2/STAT3 signal pathway form a positive feedback signal loop, mediating the interaction between MFs and lung cancer cells." (PMID 36591515, 2022). "Collectively, the finding demonstrates that plant extract, PGG, in the PI extract effectively combats lung cancer progression through autophagic cell death by altering ERK/AMPK-ULK1/STAT3 signaling axes." (PMID 35928273, 2022). "STAT3 inhibition effectively suppressed the adaptive survival of ALK-rearranged lung cancer cells by enhancing ALK inhibition-induced apoptosis." (PMID 35228642, 2022). "Loss of KLF3 potentiates lung cancer metastasis and EMT process through controlling the STAT3 pathway." (PMID 35311620, 2022).
lung carcinoma (continued). "In conclusion, we found that rhein inhibits cell proliferation and migration through the Stat3/Snail/MMP2/MMP9 pathway in lung cancer cells." (PMID 35178453, 2022). "Studies have found that constitutive activation of STAT3 can be detected in lung cancer, so it is considered to be closely related to the occurrence and development of lung cancer." (PMID 35190747, 2022). "TGF-β and IL-6/JAK2/STAT3 pathway form a positive feedback signal loop, mediating the interaction between MFs and lung cancer cells." (PMID 36591515, 2022). "Resveratrol has been shown to decrease the activity of STAT3, suppress M2 polarization of TAMs, and inhibit lung cancer growth." (PMID 35193986, 2022). "Our findings were parallel to the findings of previous studies where MALAT1 promoted drug resistance in cancer cells via modulating STAT3 activation in lung cancer and enhanced FUT4 fucosylation by sponging miR-26a/26b involving PI3K/AKT pathway." (PMID 35281907, 2022). "Since host Pdia4 in T and B lymphocytes was pivotal for lung cancer development, we then addressed how Pdia4 controlled Stat3‐mediated expression of the Vegf family in both lymphocytes." (PMID 35170261, 2022). "Many studies demonstrated that targeting the JAK2/STAT3 signal is an effective therapy for lung cancer metastasis." (PMID 35216134, 2022). "At the same time, lung cancer cells often downregulate STAT3 inhibitor SOCS3 which exacerbates the IL-6/STAT3 loop; overexpression of SOCS3 and PIAS can restore normal tumor suppression ability." (PMID 35406557, 2022). "Current study suggests these two SLs to be the promising agents for overcoming paclitaxel resistance in A549 lung cancer cells via MALAT1/STAT3/FUT4 axis." (PMID 35281907, 2022). "Research has demonstrated that abnormal JAK2/STAT3 signaling pathway activation occurs in lung cancer and other tumor tissues and tumor cells and it is engaged in the occurrence, metastasis, development, and invasion of tumors." (PMID 35789603, 2022). "Antiparasitic drugs have been demonstrated to successfully inhibit the activation of the STAT3 pathway, selectively impairing the growth of lung cancer cells and eliciting lethal effects both in vitro and in vivo." (PMID 36559280, 2022). "As a point of convergence for many oncogenic signalling pathways, STAT3 is constitutively activated at high frequency in a wide diversity of cancers including lung cancer and is a promising molecular target for cancer therapy." (PMID 35769912, 2022). "STAT3, a critical protein in tumor metastasis, including in the metastasis of lung cancer, is a valuable biomarker for prognosis prediction and is a therapeutic target in human solid tumors." (PMID 36547079, 2022). "AZD9150 (Danvartirsen) inhibits the signal transducer and activator of transcription 3 (STAT3), and has shown activity against lymphoma and lung cancer in preclinical studies." (PMID 36291769, 2022). "Nuclear factor-κB (NF-κB) and Signal transducer and activator of transcription 3 (STAT3) were the main factors affecting inflammation and cancer, and their activation promoted lung cancer cell proliferation." (PMID 36188592, 2022). "In summary, the mechanisms underlying treatment-induced adaptive cancer cell survival in residual tumors of ALK-rearranged lung cancer are predominantly dependent on STAT3 activity and subsequent transcriptional regulation of apoptosis." (PMID 35228642, 2022). "In this review, we discuss and summarize the importance of the STAT3 signaling pathway in the progress of lung cancer and the recent progress in STAT3 targeting strategies." (PMID 36559280, 2022). "Apparently, the Pdia4/Stat3/Vegf axis in T and B lymphocytes seemed to be important for lung cancer development." (PMID 35170261, 2022). "Previous studies have shown that VEGF is regulated by the STAT3 pathway in several types of cancer, including lung cancer." (PMID 36547079, 2022).
lung carcinoma (continued). "PGG can be exploited as a potential AMPK activator/STAT3 inhibitor in developing adjuvant chemotherapeutics against lung cancer." (PMID 35928273, 2022). "6-OAP was also responsible for SKP2 inhibition by inhibiting STAT3 transcriptional activity, so it exerted anti-tumor activity in lung cancer cells." (PMID 35911641, 2022). "In conclusion, SH2B3 restrained the development of anoikis resistance and EMT of lung cancer cells via suppressing JAK2/STAT3 and SHP2/Grb2/PI3K/AKT signaling cascades, leading to decreased cancer cell proliferation, migration, and invasion." (PMID 35589677, 2022). "Functional genomic screening using small guide RNA libraries showed that treatment-induced adaptive survival of ALK-rearranged lung cancer cells was predominantly dependent on STAT3 activity upon ALK inhibition." (PMID 35228642, 2022). "Other targets, such as Ataxia Telangiectasia Mutated (ATM), have been reported to upregulate PD-L1 expression via the JAK1, 2/STAT3 pathway, mediating the cisplatin-resistance in lung cancer cells." (PMID 36559280, 2022). "Taken together, our results demonstrate that SH2B3 modulates anoikis, EMT, and proliferation, migration, and invasion of lung cancer cells by suppressing JAK2/STAT3 signaling." (PMID 35589677, 2022). "Although many natural compounds have shown therapeutic effects on lung cancer by inhibiting STAT3 activation, their molecular mechanisms remain to be further studied." (PMID 36559280, 2022). "To examine the roles of STAT3 in acquired resistance of ALK-rearranged lung cancer, we evaluated STAT3 activity and effects of the combined treatment on acquired resistant ALK-rearranged cells." (PMID 35228642, 2022). "Another study demonstrated that SphK1 elevated the expression of STAT3 and facilitated the progression of non−small-cell lung cancer." (PMID 35719962, 2022). "Aberrant phosphorylation of STAT3 accumulates in nearly 70% of cancers, such as non‐small cell lung cancer and breast tumor." (PMID 35356799, 2022). "Studies have shown that lncRNA TSLNC8 significantly inhibits lung cancer cell progression and metastasis by targeting the IL-6 /STAT3/ HIF-1alpha signaling pathway." (PMID 34670194, 2021). "In vitro, leptin significantly increased the viability of lung cancer cell lines A549 and H460 in a dose-dependent manner by activation of STAT3, Bcl-2, and cyclin D1." (PMID 33708630, 2021). "Using patient-derived stem cell lines from lung-to-brain metastases, Singh and colleagues identified STAT3 and miR-21 as cooperative regulators of stemness, migration, and brain-metastasis initiation capacity of lung cancer cells." (PMID 34208282, 2021). "We demonstrated that combination EGFR blockade and STAT3 inhibition was more effective in inhibiting TKI resistant lung cancer cell xenograft growth than inhibition of either pathway alone." (PMID 33391507, 2021). "STAT3 pathway was reported to be the most critical downstream of IL-6 signaling that modulated PD-L1 in lung cancer cells." (PMID 34429133, 2021). "miR-218 was recently reported to play a tumor suppressive role in lung cancer through regulation of the IL6/STAT3 pathway." (PMID 33859751, 2021). "Stable depletion of PRMT5 profoundly reduced endogenous STAT3 phosphorylation and expression of two STAT3 targets, e.g., survivin and c‐Myc, in lung carcinoma A549 cells." (PMID 34026434, 2021). "A previous study has shown that fraxetin inhibits the proliferation of lung cancer cells by inhibiting the activation of STAT3." (PMID 33959183, 2021). "Treatment with Gal‐3 increased the expression of PD‐L1 in A549 lung cancer cells as well as STAT3 phosphorylation, whereas blocking Gal‐3 with an inhibitor decreased both the expression of PD‐L1 and STAT3 phosphorylation in these cells." (PMID 33455075, 2021). "In a similar manner, circHIPK3 modulates autophagy via MIR124-3p-STAT3-PRKAA/AMPKα signaling in STK11 mutant lung cancer cells." (PMID 34326381, 2021).